NGF (nerve growth factor)
Diseases named in the same sentence as NGF in open-access papers (continued):
Sharing a sentence is not in itself a finding about the gene and the disease.
Bell's palsy (1 paper, 2015). Partial or complete paralysis of the facial muscles of one side of a person's face. "Clearly, the efficacy and safety of NGF should be strictly assessed prior to being recommended for routine use in patients with Bell’s palsy." (PMID 25574223, 2015). "A meta-analysis was performed to evaluate the efficacy and safety of nerve growth factor (NGF) in the treatment of Bell’s palsy." (PMID 25574223, 2015). "In conclusion, the present available trials provide limited evidence on the effectiveness of NGF in the treatment of Bell’s palsy." (PMID 25574223, 2015). "The findings of the present study provide limited evidence that NGF is beneficial to the symptomatic treatment of Bell’s palsy." (PMID 25574223, 2015). "To date, however, no systematic review has provided evidence on the efficacy of NGF for Bell’s palsy." (PMID 25574223, 2015). "Assuming that NGF is beneficial in the treatment of Bell’s palsy, possible mechanisms of action are of interest." (PMID 25574223, 2015). "Therefore, we conducted a systematic review to critically evaluate the effect of NGF treatment on Bell’s palsy." (PMID 25574223, 2015). "All the available trails exhibited the positive effects of NGF in treating Bell’s palsy." (PMID 25574223, 2015). "However, evidence supporting the effectiveness of NGF for the treatment of Bell’s palsy is limited." (PMID 25574223, 2015). "Reports on the use of NGF to treat Bell’s palsy are lacking, and few trials have examined the effects of NGF treatment on Bell’s palsy." (PMID 25574223, 2015).
bowel dysfunction (1 paper, 2019). Any disease in which the causes of the disease is a perturbation of the lower digestive tract leading to its dysfunction. "These reported findings suggest that NGF-mediated signaling contributes to NMS-induced bowel dysfunctions." (PMID 30988299, 2019). "Given that blockade of NGF/TrkA effectively ameliorates the early-life stress-induced bowel dysfunctions, it appears that the NGF/TrkA axis, but not the NGF/p75 axis, plays a major role in the regulation of intestinal homeostasis under stressful conditions in early life." (PMID 30988299, 2019).
brain inflammation (1 paper, 2021). "In favor of this concept is the finding that injection of Aβ oligomers in the hippocampus of naïve rats provoked both brain inflammation and NGF dysregulation and that this NGF dysmetabolism was rescued via the application of an anti-inflammatory compound." (PMID 35011577, 2021).
Cachexia (1 paper, 2025). Severe weight loss, wasting of muscle, loss of appetite, and general debility related to a chronic disease. "In that study, it was hypothesised that the reduced nerve growth factor (NGF) levels associated with cachexia were responsible for the hypoinnervation." (PMID 39825711, 2025).
Cerebrovascular Disease (1 paper, 2018). "According to the data of Cerebrovascular Disease Knowledge Portal most recent GWAS have discovered associations between the studied sequence variants in NGF and NGFR gene and cerebrovascular disease or related traits." (PMID 29499660, 2018).
cervical disease (1 paper, 2023). "This is the first study to evaluate the immunohistochemistry expression of BDNF and NGF in the preneoplastic cervical disease according to HIV infection, possibly highlighting the role of BDNF as a mediator of cervical dysplastic and neoplastic progression, enhanced by HIV infection." (PMID 37445902, 2023). "Therefore, we aimed to investigate whether BDNF and NGF are overexpressed in preneoplastic cervical disease from HIV-infected women." (PMID 37445902, 2023).
cervical squamous cell carcinoma (1 paper, 2021). A squamous cell carcinoma arising from the cervical epithelium. "Research reveals the overexpression of NGF in cervical squamous cell carcinoma (SCC) in the mean time." (PMID 34722240, 2021).
cervical tumor (1 paper, 2021). "In order to verify the effect of NGF on cervical tumor growth and whether it correlates with the Hippo pathway, the xenograft mouse model was generated by subcutaneous injection of HeLa cell line." (PMID 34722240, 2021).
Chagas cardiomyopathy (1 paper, 2013). A disease of the cardiac muscle developed subsequent to the initial protozoan infection by trypanosoma cruzi. "TrkA residing in CFs induces an exuberant NGF production in response to T cruzi infection, enabling, in a paracrine fashion, myocytes to resist oxidative stress, a leading Chagas cardiomyopathy trigger." (PMID 23437390, 2013).
Charcot arthropathy (1 paper, 2013). "Considering these findings, BDNF and NGF, also known to be bone anabolic factors, may be upregulated in Charcot arthropathy, leading to development of intra-articular giant ectopic ossification." (PMID 24151574, 2013).
childhood cancer (1 paper, 2024). "The results from this study indicate that cisplatin treatment exacerbates NGF-mediated nociceptor sensitisation and initiates chemotherapy-induced pain in adult survivors of childhood cancer." (PMID 39428813, 2024). "Here, we used a rodent model of cisplatin-induced pain in adult survivors of childhood cancer to investigate how cisplatin-induced neuroinflammation induces nociceptor sensitisation in an NGF-dependent manner." (PMID 39428813, 2024).
Cholestatic liver disease (1 paper, 2014). "In conclusion, NGF exhibits anti-oxidative and hepatoprotective effects and is suggested to be therapeutically applicable in treating cholestatic liver diseases." (PMID 25397406, 2014).
chronic kidney disease (1 paper, 2013). Impairment of the renal function secondary to chronic kidney damage persisting for three or more months. "We previously reported elevated serum NGF levels in patients affected by glomerulonephritis, chronic kidney disease and end-stage renal disease even though we did not explore the significance of our findings." (PMID 24244623, 2013).
cobblestone lissencephaly (1 paper, 2022). "On the other hand, targeted deletion of the Ilk gene in the central nervous system in the mice model caused cortical–lamination defects typical for Cobblestone lissencephaly as well as loss of nerve growth factor (NGF) signaling." (PMID 35089438, 2022).
congestive heart failure (1 paper, 2021). Failure of the heart to pump a sufficient amount of blood to meet the needs of the body tissues, resulting in tissue congestion and edema. "In contrast with the increased cardiac NGF observed immediately after MI, as myocardial damage progresses to congestive heart failure, NGF production is reduced in humans, rats, and dogs." (PMID 34827728, 2021).
conjunctivitis (1 paper, 2007). Inflammation of the conjunctiva of the eye. "NGF is also increased in VKC blood and conjunctiva as a result of the activation of both structural (epithelium and FBs) and inflammatory cells (Th2 lymphocytes, mast cells, and eosinophils), during the active conjunctivitis." (PMID 17653039, 2007).
Creutzfeldt-Jakob disease (1 paper, 2019). "NGF might be involved also in other diseases, such as Creutzfeldt-Jakob disease, where patients had increased NGF levels in their CSF." (PMID 31105589, 2019).
Crohn disease (1 paper, 2008). A gastrointestinal disorder characterized by chronic inflammation involving all layers of the intestinal wall, noncaseating granulomas affecting the intestinal wall and regional lymph nodes, and transmural fibrosis. "Neurotrophins such as Nerve Growth Factor (NGF) increase in inflamed tissues and NGF have been shown to be increased in patients with Crohn's disease (CD) and ulcerative colitis (UC)." (PMID 18836554, 2008).
Crush Syndrome (1 paper, 2025). Severe systemic manifestation of trauma and ischemia involving soft tissues, principally skeletal muscle, due to prolonged severe crushing. "In this case series four patients—two children with hypoxic–ischemic brain injury, an adult with optic glioma-induced visual loss, and a child with severe crush syndrome—received NGF therapy after failing to recover with standard treatments." (PMID 40573325, 2025). "Following NGF treatment, all patients showed notable improvements: neurological and electrophysiological brain function improved in the children with brain injury, visual function improved in the adult with optic glioma, and the ischemic skin lesion gradually healed in the child with crush syndrome." (PMID 40573325, 2025).
cryoglobulinemia (1 paper, 2013). Cryoglobulinemia is a type of vasculitis that is caused by abnormal proteins (antibodies) in the blood called 'cryoglobulins.' At cold temperatures, these proteins become solid or gel-like, which can block blood vessels and cause a variety of health problems. "Interestingly, NGF production by B cells tended to be higher in SLE patients with cryoglobulinemia (mean fluorescence intensity, Xmean, 8.7 ± 7.7) than in patients without cryoglobulinemia (Xmean 4.1 ± 2.7, p=0.06)." (PMID 24223945, 2013).
cutaneous T-cell lymphoma (1 paper, 2016). "As for the increased level of NGF, recent study finds the correlations between levels of NGF and TARC in cutaneous T-cell lymphoma (CTCL) patients, who experience severe pruritus." (PMID 27195291, 2016).
dependent (1 paper, 2017). "For instance, nerve growth factor (NGF) is a growth factor linked to inflammatory and endocrine responses that has been reported to be altered in the blood of alcohol-dependent patients." (PMID 29108028, 2017).
developmental delay (1 paper, 2014). "As shown for past variants in this region, T546A impairs SH2B1β enhancement of nerve growth factor-induced neurite outgrowth, and the individual with the T546A variant exhibits mild developmental delay." (PMID 24971614, 2014).
diffuse large B-cell lymphoma (1 paper, 2021). "Notably, pan-pharmacological inhibition of TRKs enhanced sensitivity of diffuse large B-cell lymphoma (DLBCL) to the monoclonal antibody against CD20 rituximab 45, whereas treatment with NGF protected TRKA-transformed myeloid 32D cells against irradiation." (PMID 33456567, 2021).
dilated cardiomyopathy (1 paper, 2025). Cardiomyopathy which is characterized by dilation and contractile dysfunction of the left and right ventricles. "In this study, bioinformatics analyses and multiomics techniques were employed to elucidate the molecular mechanisms underlying dilated cardiomyopathy (DCM) and to identify five potential biomarkers: VCL, ABCB1, JAK2, KDR, and NGF." (PMID 40217309, 2025).
Dysphagia (1 paper, 2019). "There is some evidence that it can improve the cerebral blood flow and serum levels of brain-derived neurotrophic factor (BDNF) and nerve growth factor (NGF) in dysphagia patients, but still there is a lack of widely agreed evidence of a biologically-plausible basis for its effect." (PMID 31817993, 2019).
encephalitis (1 paper, 2025). An acute inflammatory process affecting the brain parenchyma. "Second, NGF levels fail to compensate for extreme circumstances, e.g., severe emerging encephalitis caused by human Borna disease virus 1 and impaired immunity caused by human immunodeficiency virus." (PMID 40783715, 2025).
encephalomyelitis (1 paper, 2021). Inflammation of the brain and the spinal cord. "NGF and its receptors, TrkA and p75NTR, are upregulated in experimentally induced encephalomyelitis in mice, a finding that supports other studies suggesting cross-talk between the nervous system and the immune system via NGF." (PMID 34572573, 2021).
ependymoblastoma (1 paper, 2024). Ependymoblastoma is a rare type of primitive neuroectodermal tumor (PNET) that usually occurs in young children under the age of 2 and is histologically distinguished by the production of ependymoblastic rosettes. "They highlighted the NGF’s role in inducing neoplastic cell differentiation in a human ependymoblastoma cell culture." (PMID 39056738, 2024). "In fact, their study results suggested that NGF did not promote neoplastic proliferation as observed in non-neuronal origin cells and stimulated ependymoblastoma cells into acquiring the structural characteristics of nerve cells." (PMID 39056738, 2024).
erythroleukemia (1 paper, 2020). Acute erythroid leukemia characterised by the presence of at least 50% erythroid precursors and at least 20% myeloblasts in the bone marrow. "Expression of CLKs in PC12 cells mimic nerve growth factor (NGF)-dependent events, including morphological differentiation and elaboration of neurites up-regulated during HMBA-induced erythroleukemia cell differentiation." (PMID 33066143, 2020).
erythromelalgia (1 paper, 2014). A rare neurovascular peripheral pain disorder due to the intermittent blockage of the blood vessels, usually in the lower extremities or hands. "The findings highlight key molecules that potentially contribute to the NGF-induced switch in nociceptors phenotype, in particular NaV1.7 which has already been identified clinically as a principal contributor to chronic pain states such as inherited erythromelalgia." (PMID 25136824, 2014).
esophageal cancer (1 paper, 2022). A primary or metastatic malignant neoplasm involving the esophagus. "Innervation has also been identified as a feature in esophageal cancer and may be driven by nerve growth factor (NGF) released from tumor cells." (PMID 35186076, 2022).
esophageal squamous cell carcinoma (1 paper, 2019). Esophageal squamous cell carcinoma (ESCC) is a type of esophageal carcinoma (EC) that can affect any part of the esophagus, but is usually located in the upper or middle third. "NGF level is 57.3 times higher in CRC than in normal colon tissue and significantly correlates with esophageal squamous cell carcinoma (ESCC) and CRC growth and metastasis." (PMID 31812953, 2019).
facial paralysis (1 paper, 2015). Severe or complete loss of facial muscle motor function. "One previous study arrived at the same conclusion subsequent to using NGF to treat traumatic facial paralysis." (PMID 25574223, 2015).
gallbladder cancer (1 paper, 2020). "Such analyses showed an increase in the nerve growth factor (NGF) and the neurotrophic tyrosine kinase receptor TrKA in gallbladder cancer glands." (PMID 33297469, 2020).
gastric ulcer (1 paper, 2021). An ulcerated lesion in the mucosal surface of the stomach. "The molecular events in granulation tissue that contribute to the mechanisms of gastric ulcer healing include the activation of genes encoding bFGF, FGF-R1,2,4, VEGF, and flk-1/KDR; Ang 1 and Ang 2; Tie 2 receptor; COX-2; SRF; NGF; SDF-1; and BMD-EPC via the activation of PI3K/Akt pathway." (PMID 34440733, 2021). "The role of NGF in gastric ulcer healing had not been explored before." (PMID 34440733, 2021).
gastritis (1 paper, 2019). Inflammation of the stomach. "Bielefeldt found that the expression of NGF in the gastric wall is increased in rats with gastritis and that it causes peripheral sensitization by acting on primary afferent neurons." (PMID 31856738, 2019).
glomerulonephritis (1 paper, 2021). A renal disorder characterized by damage in the glomeruli. "Other findings also disclosed an increased serum level of NGF, as well as higher NGF receptor expression in PBMCs of glomerulonephritis patients." (PMID 33874912, 2021).
Glucose intolerance (1 paper, 2025). Glucose intolerance (GI) can be defined as dysglycemia that comprises both prediabetes and diabetes. "Targeted deletion of vascular NGF or β-cell TrkA impairs GSIS and provokes glucose intolerance, whereas exogenous NGF enhances GSIS in human islets without elevating basal insulin output." (PMID 41471293, 2025).
GM1 gangliosidosis type 1 (1 paper, 2025). GM1 gangliosidosis type 1 is the severe infantile form of GM1 gangliosidosis with variable neurological and systemic manifestations. "They hypothesized that the accumulated metabolites in MPS 1 and GM1 gangliosidosis type 1 bind tightly to Trk, which also serves as a molecular receptor for NGF." (PMID 41226457, 2025).
head injuries (1 paper, 2025). "Although additional controlled, randomized, double-blind studies are necessary to elucidate the neuroprotective effects of this neurotrophin, intranasal NGF shows great promise as a therapeutic option for children facing neurological challenges after significant head injuries." (PMID 40005977, 2025).
head-neck carcinoma (1 paper, 2025). "Like in nerve tumours, NGF is upregulated in head-neck carcinoma, indicating a potential oncogenic role of NGF." (PMID 40783715, 2025).
helminth infection (1 paper, 2013). "Correale and colleagues showed increased production of BDNF and nerve growth factor in stimulated B cells from MS patients with a helminth infection compared to uninfected patients and controls." (PMID 24351232, 2013).
hemorrhagic stroke (1 paper, 2015). A stroke caused by a bleed on the brain. "For example, one hemorrhagic stroke study showed that infusion of nano-particle bound rEPO led to more than a two-fold increase in BDNF and NGF expression." (PMID 25942688, 2015).
Hernia (1 paper, 2022). "NGF immunochemistry on ProFlor specimens, followed up from the ST, through MT, LT, and ET post implantation, demonstrated the progressive imprinting of this growth factor in newly developed tissue in the 3D hernia device." (PMID 36412894, 2022). "The average percentage immunohistochemical positive cells to NGF and NGFR p75 of 15 biopsies excised from the 3D dynamic hernia scaffold at different stages post implantation were compared with a one-way Anova and post hoc Tuckey test." (PMID 36412894, 2022).
Hodgkins lymphoma (1 paper, 2018). A heterogeneous group of malignant lymphoid neoplasms of B-cell origin characterized histologically by the presence of Hodgkin and Reed-Sternberg (HRS) cells in the vast majority of cases. "Neurotrophin and NGF signaling pathways are thought to contribute to non-Hodgkin and Hodgkin lymphomas, respectively, which are highly associated with the patients with EBV infection." (PMID 30133498, 2018).
Hyperinsulinemia (1 paper, 2025). An increased concentration of insulin in the blood. "Interestingly, a study carried out in bottlenose dolphins characterized by hyperinsulinemia found, by immunolocalization, the presence of NGF and BDNF in the pancreas, which may be involved in the hyperinsulinemia that is observed in dolphins." (PMID 39857710, 2025).
hypertriglyceridemia (1 paper, 2022). A laboratory test result indicating elevated triglyceride concentration in the blood. "In the present study, women who were in the higher tertile of serum NGF had a significant lower risk of hypertriglyceridemia and MetS compared to the reference group." (PMID 35620753, 2022). "Women who were in the higher tertile of serum NGF levels had a significantly lower risk for development of hypertriglyceridemia after adjustment for potential confounding variables (OR=0.091, 95% CI: 0.023-0.361 and OR=0.193, 95% CI: 0.057-0.649 respectively)." (PMID 35620753, 2022). "Women who were in the higher tertile of serum NGF levels had significantly lower risk of hypertriglyceridemia (OR = 0.103, 95% CI: 0.028-0.374, P trend = 0.001) and MetS (OR = 0.220, 95% CI: 0.074-0.648, P trend = 0.008) compared to the reference group." (PMID 35620753, 2022). "In the current study, serum levels of obestatin, NGF, and ghrelin were associated with some CMR factors such as hypertriglyceridemia and MetS." (PMID 35620753, 2022).
immune complex disease (1 paper, 2025). "In the NGF vaccine mouse study, even at peak antibody titers, there were no signs of immune complex disease." (PMID 41012116, 2025). "In the NGF vaccine tested in mice, there were no signs of immune complex disease or neurological alterations." (PMID 41012116, 2025).
Immunodeficiency (1 paper, 2020). Failure of the immune system to protect the body adequately from infection, due to the absence or insufficiency of some component process or substance. "Additionally, some genes involved in our signature, such as TAP1 and NGF, are linked to immunodeficiency 44, 45, whose mutations may destroy the immune system and drive the aberrant mutation accumulation in somatic cells." (PMID 31949492, 2020).